Y_RNA (Y RNA )
Gene: Miscellaneous RNA gene on chromosome 6 (87,826,173 to 87,826,285, reverse strand). Ensembl gene ENSG00000207131.
Homologues: Orthologues: chimpanzee Y_RNA (100% identical), macaque Y_RNA (93% identical). Paralogues in human: RNY1 (89% identical), Y_RNA (88% identical), RNY1P11 (87% identical), Y_RNA (87% identical), Y_RNA (86% identical), Y_RNA (85% identical), Y_RNA (84% identical), RNY1P10 (83% identical), RNY1P8 (83% identical), Y_RNA (83% identical), RNY1P5 (82% identical), Y_RNA (82% identical), and 96 more.